GLI1 (GLI family zinc finger 1)
Diseases named in the same sentence as GLI1 in open-access papers (continued):
Sharing a sentence is not in itself a finding about the gene and the disease.
glioma (continued). "Glioma-associated oncogene homolog 1 (Gli-1), originally identified in human glioma cells, is a zinc finger-containing transcription factor and the main nuclear mediator of the Sonic Hedgehog (SHH) signaling pathway that regulate cell proliferation and differentiation during CNS development." (PMID 29867331, 2018). "Our previous study showed that Gli1 was a potential target to alleviate multidrug resistance of human glioma by regulating the transcription of a series of chemoresistance-associated genes, but the relationship between HH/Gli1 signaling and MGMT expression in GBM is yet to be clarified." (PMID 29225516, 2017). "The intriguing finding is that Gli1 transcriptionally activates USP48 in glioma cells, thereby establishing a positive feedback loop that governs Hh signaling." (PMID 40034124, 2025). "In human gliomas the Hh/GLI1 pathway plays an important role in the self-renewal and tumorigenicity of cancer stem cell-like cells." (PMID 40255562, 2025). "Glioma-associated oncogene 1 (GLI1), a transcription factor activated by the Sonic hedgehog pathway, plays a role in the development of various tumors, including gliomas, alveolar rhabdomyosarcomas, and osteosarcomas." (PMID 38228904, 2024). "There is an additional truncated isoform of the GLI1 protein, known as tGLI1, that has been shown to stimulate the motility and invasiveness of glioma cells." (PMID 36675073, 2023). "The MVP gene is a target of the transcription factor GLI family zinc finger 1 (GLI1), which is abnormally active in glioma lines." (PMID 37242681, 2023). "Glioma-related oncogene homolog 1 (Gli1) was originally named in glioma research, which can affect glioma cell apoptosis and proliferation via regulated cyclin D1 and Bcl-2." (PMID 35874843, 2022). "GLI1, along with its truncated homolog (TGLI1), which behaves as gain-of-function GLI1, were reportedly shown to mediate angiogenesis in gliomas by targeting the VEGF, MMP2, MMP9, VEGF-C, TEM7, and proangiogenic heparanase (HPSE) genes, respectively." (PMID 35409080, 2022). "Expression of FOXM1B, the predominant isoform of FOXM1 expressed in human gliomas, strongly correlated with poor prognosis and was regulated by GLI1." (PMID 36010600, 2022). "Insulin receptor substrate I (IRSI) in glioma stem cells (GSCs) was determined to be a GLI1 transcriptional target; furthermore, GLI1 inhibition was found to antagonize IRSI-mediated MAPK pathway activation and obstruct IGF-I mediated cell survival in GSCs." (PMID 36010600, 2022). "Of note, the GLI family zinc finger 1 (GLI1), which is a known glioma-associated oncogene, is a crucial transcription factor in the hedgehog signaling pathway." (PMID 35406554, 2022). "NANOG is also transcribed by GLI1 activation, and they both constitute an axis that promotes stemness and growth in gliomas." (PMID 34638956, 2021). "Recently, aspirin was reported to exert its antineoplastic property in glioma by abrogating the tumorigenic effect of the SHH/GLI1 signaling pathway, especially sensitizing the malignant glioma cells resistant to temozolomide (TMZ) therapy." (PMID 33494284, 2021). "The sesquiterpene, buddlindeterpene B, shows affinity for the transcription factors GLI1 and GLI2 (glioma-associated oncogen, which are zinc finger proteins)." (PMID 34356473, 2021). "In human gliomas, the Hh/Gli1 pathway plays an important role in CSC self-renewal and tumorigenicity." (PMID 32430068, 2020). "Given that the GLI1 amplification was discovered in gliomas, it is self-evident that aberrant SHH signaling plays a central role in glioma pathogenesis and tumor progression." (PMID 32957513, 2020). "It should be noted that its gene is a target of the transcription factor GLI1, which according to our previous data is abnormally active in these glioma lines." (PMID 32708613, 2020). "The GLI1 isoforms C’ΔGLI1 and N’ΔGLI1 were observed following transfection of U251 glioma cells with an N-terminal myc-tagged GLI1 expression plasmid." (PMID 32957513, 2020).
glioma (continued). "Further characterization revealed that SHH-mediated GLI1 signaling regulated the self-renewal of CD133+ glioma CSCs." (PMID 32957513, 2020). "The specific function of USP48 on GLI1 promotes the proliferation and the colony formation of glioma cells in vitro." (PMID 32531973, 2020). "Previously, we have shown the increased levels of stem cell genes, including SOX2, OCT4, and GLI1 in these glioma cell lines that coincide with the presence of the CD44 and TNC in all the exosome samples from CCM." (PMID 32708613, 2020). "Abnormally activated Hh/Gli1 pathway in gliomas promotes tumor microvessel formation, and Gli1 overexpression in esophageal tumors significantly correlates with increased microvessel density." (PMID 32430068, 2020). "We performed Western-blotting of gli1 and gli3 proteins for four primary glioma cell lines, but the data were unexpected." (PMID 30730955, 2019). "We established the overexpression of Gli1 in murine glioma cells (GL261) and GlaB effect on cell viability." (PMID 31455353, 2019). "In order to investigate Hh signaling in glioma, we measured the expression of Gli1 by RT-PCR and by immunofluorescence." (PMID 31455353, 2019). "HDAC6 maintains glioma stem cells (GSCs) through GLI1 signaling and its specific inhibition, when combined with X-ray irradiation, suppresses the tumorigenic capacity of GSCs in vivo." (PMID 30804456, 2019). "In this study, we found that GlaB treatment of GL261 glioma cells inhibits Gli1 transcription, reducing glioma cell growth." (PMID 31455353, 2019). "According to our data, treatment of glioma cells with GANT61 or siRNA against GLI1, GLI2, or GLI3 resulted in their death, indicating, that gli contribute to glioma cells survival." (PMID 30730955, 2019). "GLI1 gene has been originally isolated from human glioma cells where it was found being amplified more than 50-fold." (PMID 30158435, 2018). "Considering that GLI1, a crucial trans-cription factor, played important roles in the glioma cell phenotype, we verified that aspirin reduced cell growth in a dose- and time-dependent manner." (PMID 28446712, 2017). "Here we confirm that aspirin exerts antineoplastic property in glioma by abrogating the tumorigenic effect of the SHH/GLI1 signaling pathway and acquire in-depth knowledge of sensitizing route of aspirin to TMZ therapy." (PMID 28446712, 2017). "We found that GDC-0449 treatment significantly decreased the expression levels of Gli1 and Gli2 in glioma cells." (PMID 28195165, 2017). "Silencing of GLI1 expression with siRNA in human glioma cells reduced the levels of SPP1 expression and protein secretion." (PMID 28030801, 2017). "Instead, glioma-associated oncogene 1 (GLI1) and oligodendrocyte lineage transcription factor 2 (OLIG2), the expression of which is highly associated with glioma and GSCs, were upregulated." (PMID 28830458, 2017). "SHH/GLI1 signaling pathway was important to maintain the growth invasion and anti-apoptosis of glioma cell." (PMID 28446712, 2017). "Further studies showed that 66.7% primary and recurrent gliomas showed Gli1-nuclear expression, which positively correlated with glioma progression." (PMID 28899410, 2017). "Collectively, aspirin has a therapeutic potential for SHH/GLI1 targeted therapy against glioma cells." (PMID 28446712, 2017). "Knockdown of GLI1 expression in glioma cells significantly reduced the levels of SPP1 mRNA and protein production." (PMID 28030801, 2017). "We also searched the Gene Expression Omnibus (GEO) from NCBI database, and found that in glioma, higher GLI1 expression is significantly correlated with higher tumor grades." (PMID 28562331, 2017). "The lack of PTCH repression allows SMO to initiate a series of intracellular events that culminate in the activation of the GLI (Glioma) family of zinc finger transcription factors, i.e., GLI1, GLI2 and GLI3." (PMID 27548161, 2016).
glioma (continued). "Tumor ECs expressed SHH in a PDGF-driven mouse glioma model, providing a potential mechanism for GLI1 activation in GSCs." (PMID 26977157, 2016). "In fact, Gli1 was first identified as an amplified, highly expressed factor in human glioma, and an oncogenic transcription factor being responsible for the carcinogenesis of sporadic basal cell carcinoma." (PMID 25265279, 2014). "Further, we indicated that ectopic expression of Sufu suppresses glioma cell growth, invasiveness, and angiogenesis through Hedgehog signaling pathway via Gli1 directly binding and subcellular distribution both in vitro and in vivo." (PMID 25373737, 2014). "Apart from SHH, experimental evidence also showed that ERK12, TWIST and RAS proteins were up regulated during Glioma and these were known to have a direct effect on the abnormal activation of GLI1 and GLI2." (PMID 23935937, 2013). "Consistent with the isolation of Gli1 from glioma cells, activation of the Hedgehog-Gli1 pathway is reported in GBM, which is required for the clonogenicity and formation of secondary neurospheres of CD133+ GICs." (PMID 22400111, 2012). "Gli1, the founding member, was initially identified as being highly amplified in gliomas, and Gli2 and Gli3 were subsequently cloned by hybridization." (PMID 20865152, 2010). "GLI1 regulates stem cell renewal and tumorigenicity of gliomas, and targeted inhibition of the Hedgehog pathway results in partial tumor regression in animal models." (PMID 20838435, 2010). "Gli1 and Gli2 control the expression of Bmi‐1 by their binding to the Bmi‐1 promoter and eventually upregulating multidrug‐resistant proteins that promote chemoresistance in glioma cells." (PMID 39791545, 2025). "In vivo experiments demonstrated that GlaB inhibits glioma cell growth and exacerbates the Warburg effect; by inhibiting GLI1 and lactate efflux at the same time, the antitumour effect in vivo was enhanced, providing a new therapeutical strategy for this brain tumour." (PMID 38399442, 2024). "Herein, we describe a selection of oncogenic (GLI-1/2/3, E2F1–8, STAT3, and HIF-1/2) and tumor suppressor (NFI-A/B, TBXT, MYT1, and MYT1L) TFs that are deregulated in gliomas and are subsequently associated with tumor development, progression, and migratory potential." (PMID 35409080, 2022). "In addition, aspirin sensitizes malignant glioma cells to temozolomide therapy by inhibiting the SHH/GLI1 signaling pathway, preventing most GLI1 translocation into the nucleus and resulting in higher expression levels in the cytoplasm." (PMID 35785194, 2022). "Since the 1987 discovery of GLI1 in human glioma cells, the role of the three members GLI1, GLI2 and GLI3 in a variety of cancers has become increasingly apparent, with GLI1 expression specifically identified as a negative prognostic factor in numerous cancers." (PMID 34639011, 2021). "In addition to USP7 and OTUB2, the deubiquitinase USP48 was found to activate Hh signaling by stabilizing Gli1 protein in glioma cells." (PMID 34948134, 2021). "For example, GLI1 is amplified in glioma, osteosarcoma, and rhabdomyosarcoma." (PMID 34113570, 2021). "Interestingly, USP48 is transcriptionally activated by Gli1 in glioma cells, thus forms a positive feedback loop to regulate Hh signaling." (PMID 34948134, 2021). "Taken together, hypoxia may potentially regulate TMZ resistance in glioma cells through the HIF-1α/Shh/GLI1 axis." (PMID 34638233, 2021). "Moreover, mGluR4 activation negatively regulated the expression of Gli-1, whose activity plays essential roles in controlling the growth of glioma cells." (PMID 29867331, 2018). "Acquired activation of GLI1 protects glioma cells against TMZ therapy." (PMID 28446712, 2017). "We hypothesized that aspirin may abrogate the activity of GLI1 to inhibit the glioma cells malignancy." (PMID 28446712, 2017).
glioma (continued). "Given that NF-κB is known to be activated by genotoxic agent, alkylating agents, which might play a role in the acquired overexpressed GLI1 from glioma cells responding to TMZ therapy." (PMID 28446712, 2017). "Importantly, the simulative effect of SMO agonist purmorphamine on GLI1 activity in U-87 MG glioma cells was dramatically arrogated by NUSAP1 depletion." (PMID 28899410, 2017). "GLI1 is the first found Hh relative gene amplified in a human glioma." (PMID 28562331, 2017). "A similar pattern of tumor recurrence was also observed in GLI1 overexpressing glioma cells." (PMID 26633513, 2015). "The inactivation of the SHH/GLI1 pathway mediated the anti-glioma effects of curcumin." (PMID 26563263, 2015). "Additionally, GLI1 overexpression-induced MDR has been correlated with the recurrence of glioma after chemotherapy." (PMID 26633513, 2015). "Accordingly, the latent mechanism of Sufu effects on glioma biological behavior could be owed to the inhibition of Gli1 transcription and suppression of downstream genes." (PMID 25373737, 2014). "Therefore, to investigate how Sufu influence glioma cells, we firstly detected Gli1 and Sufu mRNA expression changes after transfection." (PMID 25373737, 2014). "Here, we demonstrated that combination chemotherapy – incorporating a Smo inhibitor and Gli1 suppressor – could benefit glioma patients of traditional drug resistance, especially those resistant to Cyclopamine." (PMID 25373737, 2014). "To determine whether the inverse relationship between Sufu and Gli1 expression was consistent in vitro and in patient samples, we quantified expression levels of Sufu and Gli1 in glioma tissue specimens by IHC assay and datasets analysis." (PMID 25373737, 2014). "High-grade glioma contained comparatively lower Sufu expression and higher Gli1." (PMID 25373737, 2014). "Indeed, genetic or pharmacological inhibition of GLI1 decreases IGF-I induced glioma stem cells self-renewal, proliferation, migration, angiogenesis, and IGF dependent MAPK activation." (PMID 24550888, 2014). "Therefore, Gli1 is an ideal candidate target for gliomas gene therapy." (PMID 35874843, 2022). "Finally, high Gli1 expression levels have been correlated with increased microvascular density in Glioma and high KDR expression in triple-negative breast cancers while Ihh expression has been associated with Vegf expression and CD34 staining in hepatocellular carcinoma." (PMID 31238510, 2019). "Hence, the inhibitory effect of mGluR4 activation on the growth of LN229 GMB cells might be due to suppression of the abnormal expression of Gli-1, which may restrict the activity of glioma stem cells." (PMID 29867331, 2018). "So, targeting the GLI1 might become a novel and potential therapeutic strategy for glioma." (PMID 28446712, 2017). "Moreover, we found that, in response to SMO agonist purmorphamine treatment, the activity of GLI1 was only slightly increased in SW 1088 glioma cells, which displays low NUSAP1 expression, but significantly increased in U-87 MG glioma cells, which exhibits high NUSAP1 expression." (PMID 28899410, 2017). "Next, we analyzed whether inhibition of GLI1 influenced DNA damage and repair in the glioma cells." (PMID 28446712, 2017). "Subsequently, to investigate the aspirin associated apoptotic route via SHH/GLI1 inhibition at protein level, Western blot showed that Caspase-3, Bax and cleaved PARP increased in a dosedependent manner and that Bcl-2, an anti-apoptosis protein, decreased in the glioma cells treated by aspirin." (PMID 28446712, 2017). "A HH/Gli1 inhibitor (GANT61) was found to sensitize U87MG and U251MG glioma cells to TMZ treatment by enhancing the DNA damage effect, suppressing MGMT expression and the Notch1 pathway." (PMID 36675073, 2023). "Hedgehog/Gli1 pathways are often found overactivated in GBM, and Sonic Hedgehog (SHH) is the most researched hedgehog in EMT in gliomas." (PMID 36338770, 2022).
glioma (continued). "Conversely, the degradation of HIF-1α by oroxylin A or the inhibition of Hh/GLI1 signaling by cyclopamine led to the downregulation of the HIF-1α/Hh pathway and the increased expression of SUFU, thus restoring glioma cells’ chemosensitivity to TMZ." (PMID 34638233, 2021). "The expression of GLI1, GLI2, GLI3 and their target genes FOXM1 and BMI1 was analyzed by RT-qPCR for 20 glioma cell lines and a normal adult brain tissue." (PMID 30730955, 2019). "The incubation of glioma cells with siRNA against GLI1, GLI2, or GLI3 resulted in death of glioma cells." (PMID 30730955, 2019). "In our study, we found that SUV39H2 regulated the activity of the GLI1 reporter, and there was a reverse correlation between SUV39H2 and HHIP expression in glioma." (PMID 31636512, 2019). "In A172 glioma cells, mRNA levels of IGF2, Gli1, and Myc were significantly downregulated in Lnc-THOR-silenced or Lnc-THOR-KO A172 cells." (PMID 31727877, 2019). "The treatment of glioma cells with cyclopamine, GANT61 or siRNA against GLI1, GLI2, or GLI3 significantly decreased the expression of GLI1, FOXM1, BMI1, SOX2, and OCT4, involving in the maintenance of the stem cell state." (PMID 30730955, 2019). "Aspirin acted as the glioma growth-inhibitory and pro-apoptosis roles by inhibiting the SHH/GLI1 pathway and reprogramming the epithelial to mesenchymal transition (EMT)." (PMID 28446712, 2017). "The transcriptional regulation of the SPP1 expression by GLI1 (and likely OCT4) in glioma cells resembles the stem cell-type regulation." (PMID 28030801, 2017). "Meanwhile, the Foxm1 gene downstream of GLI1, via targeting CyclinD1 and MMP-2 and regulating TGF-β1 signaling, is critical in promoting EMT of glioma cells." (PMID 28446712, 2017). "Aspirin alone was used to treat glioma cell lines, and that concentrations of aspirin from 1 to 10 mM inhibited the SHH/GLI1 signaling pathway significantly." (PMID 28446712, 2017). "Because we found short time of aspirin administration promoted GLI1 expression in vitro and in vivo, low-dose of aspirin with limited side effects was repurposed to overcome TMZ resistance of glioma." (PMID 28446712, 2017). "The cytotoxicity of a Gli1/2 inhibitor, GANT61 was examined both alone and in combination with TMZ in human glioma cell lines." (PMID 27894350, 2016). "In the present study, we investigated the effect of Gli1/2 downregulation by GANT61 on TMZ induced cytotoxicity in U87 and U251 glioma cells." (PMID 27894350, 2016). "We found that compared to GLI1, GLI2 was more potential activator of Glioma scenario as it was connected with GLI1 which was also an important activator in the network." (PMID 23935937, 2013). "On the other hand SHH, SMO, GLI1, GLI2, GLI3_A (core Hedgehog pathway molecules) were activating the other proteins in both normal as well as Glioma scenarios." (PMID 23935937, 2013). "In addition, the GLI1 expression levels were particularly high in grade III and IV gliomas, whereas GLI2 was found overexpressed only in grade III tumors." (PMID 35409080, 2022). "In human glioblastoma, USP48 and Gli1 expression levels were positively correlated, and high USP48 expression levels correlated with higher grades of glioma malignancy, suggesting that the USP48-Gli1 regulatory axis is critical for glioma cell proliferation and glioblastoma tumorigenesis." (PMID 34948134, 2021). "Treatment with GANT61 or siRNA against GLI1, GLI2, or GLI3 could result in complete glioma cell death, while cyclopamine had a weaker and line-specific effect on glioma cell survival." (PMID 30730955, 2019). "Thus, the expression of the components of the Shh signaling pathway, including GLI1, GLI2, GLI3, PTCH, and SMO, was found to be common in various tumors of the nervous system, including gliomas, and correlated with a poor prognosis of patient survival." (PMID 30730955, 2019).